ENPP7P13 (ectonucleotide pyrophosphatase/phosphodiesterase 7 pseudogene 13)
Synonyms: DUNQU1
Gene: Processed pseudogene on chromosome 16 (33,769,421 to 33,769,679, forward strand). Ensembl gene ENSG00000261580.
Diseases named in the same sentence as ENPP7P13 in open-access papers:
ENPP7P13 is named in the same sentence as 1 disease in open-access papers, as found by Europe PMC text mining. Sharing a sentence is not in itself a finding about the gene and the disease.
ENPP7P13 shares sentences with these, for which no sentence is quoted: cancer (1 paper).